EGFR (epidermal growth factor receptor)
Diseases named in the same sentence as EGFR in open-access papers (continued):
Sharing a sentence is not in itself a finding about the gene and the disease.
triple-negative breast carcinoma (continued). "In vivo combination therapy of EGFR-specific CAR T cells with the CDK7 inhibitor THZ1 showed a suppression of immune resistance, tumor growth, and metastasis in triple-negative breast cancer models." (PMID 35203517, 2022). "Studies showed that NK1R regulated the growth of triple-negative breast cancer (TNBC) by transactivating EGFR phosphorylation and affected the therapeutic effect of EGFR mAb cetuximab." (PMID 35013118, 2022). "In the triple-negative breast cancer MDA-MB-231 cell line, stimulation of the epidermal growth factor receptor (EGFR) increased ABL2 activity and promoted cortactin-mediated invadopodia formation." (PMID 34022881, 2021). "Of note, in triple-negative breast cancer (TNBC) cells, it was shown that epidermal growth factor (EGF) signaling activates the first step of glycolysis, and F-1,6-BP directly binds to epidermal growth factor receptor (EGFR), enhancing its activity." (PMID 34205414, 2021). "EGFR is another kinase that phosphorylates PARP1, and the inhibition of both EGFR and PARP1 results in synthetic lethality in highly aggressive triple negative breast cancers (TNBCs)." (PMID 34639169, 2021). "The triple-negative breast cancer (TNBC) lacks the expression of the hormone receptors and the amplification of HER2, and commonly overexpresses the epidermal growth factor receptor (EGFR)." (PMID 34729098, 2021). "Chained strand displacement events are triggered after the capture probes detect the surface biomarkers epidermal growth factor receptor (EGFR) and intercellular adhesion molecule-1 (ICAM-1) in the triple-negative breast cancer cell MDA-MB-231." (PMID 34745974, 2021). "Recently, we found that dual inhibition of epidermal growth factor receptor (EGFR) and MET kinase activities resulted in the synergistic anti-proliferation effect through downregulation of RPS6 in triple-negative breast cancer (TNBC) cells." (PMID 35008473, 2021). "In triple-negative breast cancer cells, the FER-dependent phosphorylation of PKCδ enhances EGFR signaling and promotes anchorage-independent cell growth." (PMID 33411917, 2021). "We investigated the role of SHP2 in the responsiveness to EGF by using the EGFR-amplified cell line MDA-MB-468, derived from a patient with triple-negative breast cancer." (PMID 33755016, 2021). "In preclinical models of triple-negative breast cancer (TNBC) with intact DNA repair, we have previously shown an induced synthetic lethality with combined EGFR inhibition and PARPi." (PMID 33663560, 2021). "Triple-negative breast cancer (TNBC) is highly recurring and metastatic breast cancer with overexpressing epidermal growth factor receptor (EGFR)." (PMID 34298600, 2021). "Recent work revealed that in triple-negative breast cancer (TNBC) KLF4 is a repressor of the EGFR gene leading to a decrease in both total and phosphorylated EGFR levels in MDA-MB-231 and MDA-MB-468 cells." (PMID 33266506, 2020). "Cetuximab was tested in a phase II trial of 31 patients with triple negative breast cancer (TNBC), and only 2/31 patients responded to treatment, despite the majority of tumors exhibiting over-expression of EGFR." (PMID 31597954, 2020). "To evaluate the co-expression of EGFR and BCL-2/XL within patient triple-negative tumors, we utilized a human tumor microarray (HTMA-240) comprising triple-negative breast cancers." (PMID 33256808, 2020). "Basal-like breast cancer (BLBC) is a subgroup of triple-negative breast cancer (TNBC) that expresses high levels of certain proteins, such as keratins (CK5/6, CK14, CK17), epidermal growth factor receptor (EGFR), c-Kit, and vimentin." (PMID 32364614, 2020). "These novel data emphasize the functional role of EGFR signaling in modulating cell morphology in MDA-MB-231 (ERβ-positive) and shERβ MDA-MB-231 (ERβ-suppressed) triple-negative breast cancer cells." (PMID 33050027, 2020).
triple-negative breast carcinoma (continued). "Targeted therapies for triple-negative breast cancer (TNBC) are limited; however, the epidermal growth factor receptor (EGFR) represents a potential target, as the majority of TNBC express EGFR." (PMID 33256808, 2020). "In triple-negative breast cancer (TNBC), the most aggressive type of the disease with the worst prognosis mainly due to relapse, epidermal growth factor receptor (EGFR) is significantly overexpressed." (PMID 33050027, 2020). "Additionally, data suggest that blocking EGFR can effectively increase the antitumor activity of selumetinib in triple-negative breast cancer, which may be related to the effect of this combination on the activation of extracellular signal-regulated kinase 1/2 and AKT." (PMID 32685551, 2020). "Epidermal growth factor receptor (EGFR) and human epidermal growth factor receptor 3 (HER3) have been investigated as triple-negative breast cancer (TNBC) biomarkers." (PMID 32080212, 2020). "Overexpressed epidermal growth factor receptor (EGFR) and overactivated epithelial-mesenchymal transition (EMT) in triple-negative breast cancer (TNBC) can enhance tumorigenesis and tumor recurrence and metastasis." (PMID 31214503, 2019). "Targeting EGFR/HER1, which is expressed in most patients of triple-negative breast cancer, or its signaling is a novel and attractive strategy." (PMID 30347895, 2018). "Th1 cytokines induced minimal senescence or apoptosis in triple negative breast cancer cells (TNBC); however, inhibition of EGFR in combination with Th1 cytokines sensitized those cells causing both senescence and apoptosis." (PMID 29796172, 2018). "Mek inhibition induces increased Axl and Her2 levels in triple negative breast cancer (TNBC) cells while Met and EGFR levels remain unchanged, with Axl and Her2 sharing re-wiring through increased synthesis and differing secondary contributing mechanisms." (PMID 30524510, 2018). "The EGFR targeted method is one of the optimistic strategies for TNBC treatment and successfully can improve the therapeutic efficacy in triple negative breast cancer patients." (PMID 30408068, 2018). "We then collected 20 samples of triple-negative breast cancer paired with adjacent normal mammary tissues and analyzed by western blotting for the expression of ZNF516 and EGFR." (PMID 28947780, 2017). "EGFR and PTEN protein levels were analyzed in different subclones of MDA-MB-231 triple-negative breast cancer cell lines by immunoblotting." (PMID 28008153, 2017). "Surprisingly, FGD3 mRNA expression in BT-20, a triple-negative breast cancer cell line, was upregulated to 1.99 and ESR1 was upregulated to 0.47 on a log2 scale when treated with an EGFR inhibitor." (PMID 32913979, 2017). "In this relation, it has already been demonstrated in triple negative breast cancer cell lines, that combining PI3K and EGFR inhibitors produces a better response than each inhibitor alone becoming a promising strategy for BRCAness tumors treatment." (PMID 26979459, 2016). "The aim of this study was to examine the expression of the EGFR, CK5, and Ki-67 among triple-negative breast cancer cases and to correlate the expression of the basal markers with the clinicopathological prognostic parameters." (PMID 25400978, 2014). "Epidermal growth factor receptor, EGFR (HER1), over-expressed in triple negative breast cancers, was down-regulated in MDA-MB-231 cells by NP109 in the dose response and time course studies." (PMID 23516601, 2013). "Several basal-related genes directly corresponding to expression levels of cytokeratins and EGFR protein marker, including KRT5, KRT6C, KRT6E, KRT14, and EGFR genes, were found to be extensively up-regulated in triple-negative breast cancer." (PMID 23049873, 2012).
triple-negative breast carcinoma (continued). "The results of this study suggest that tumor-targeted nanobioconjugate carrying EGFR AON with significant anti-tumor activity against EGFR-positive TNBC may represent a new generation of cancer therapeutics with a potential for efficacy against triple negative breast cancers." (PMID 22355336, 2012). "EGFR is one of the prominent hallmarks of triple negative breast cancer (TNBC) and/or BPBC and over-expression of EGFR has been used as a main therapeutic target for treatment of TNBC." (PMID 22496908, 2012). "Frequently increased EGFR copy number and EGFR protein expression, and decreased BRCA1 mRNA expression, were observed in Japanese triple-negative breast cancers." (PMID 18950515, 2008). "In contrast to single-pathway inducers, SH003 may amplify via multi-node interference, sensitizing ferroptosis-resistant tumor types such as triple-negative breast cancer (TNBC) and epidermal growth factor receptor (EGFR)-mutant NSCLC." (PMID 41228309, 2025). "Additionally, fibroblast secretion of HGF was found to activate MET and lead to EGFR/MET crosstalk, resulting in resistance to EGFR TKIs in triple-negative breast cancer." (PMID 40560045, 2025). "Similarly, TET1, an epigenetic modulator overexpressed in CAFs, reshapes the CAF epigenome by hypomethylating oncogenic pathways (e.g., PI3K, EGFR, PDGF) in triple-negative breast cancer." (PMID 40216762, 2025). "For instance, it can be investigated whether ISL can inhibit the metastatic progression of digestive system tumors by regulating the circNAV3/miR-4262/ST6GALNAC5/EGFR axis, which is analogous to ISL’s role in triple-negative breast cancer." (PMID 40978472, 2025). "Finally, simultaneous inhibition of epidermal growth factor receptor (EGFR) and ROCK has been shown to be a promising strategy for treating triple-negative breast cancer, as revealed by shRNA screening." (PMID 39458584, 2024). "In addition, EGFR CAR T cells activated the interferon γ, granzyme-perforin-PARP, and Fas-FADD-caspase signaling pathways in triple-negative breast cancer." (PMID 36707873, 2023). "Another phase II trial of anti-EGFR ILs-dox in advanced triple-negative breast cancer (NCT02833766) did not meet its primary endpoint of progression-free survival at 12 months." (PMID 37754880, 2023). "Indeed, F-1,6-BP can bind to the epidermal growth factor receptor (EGFR), as shown in triple negative breast cancer cells, thus enhancing EGFR activity." (PMID 35626081, 2022). "EGFR has the highest DGA score for breast adenocarcinoma likely because it is hyper-expressed in approximately half of the cases of inflammatory breast cancer and triple-negative breast cancer." (PMID 35601606, 2022). "Furthermore, TLR9 overexpression in triple-negative breast cancer leads to epithelial-to-mesenchymal transition (EMT) induction and EGFR pathway deregulation, suggesting a role in the carcinogenesis of this tumor subtype." (PMID 34573939, 2021). "Increased expression and/or gene amplification of EGFR have been observed in many human cancers including triple negative breast cancer and, accordingly, MDA-MB-231 cells express high levels of EGFR compared to MCF7 cells that belong to the luminal A subtype 26,58,59." (PMID 33633298, 2021). "To find metastatic recurrence biomarkers of triple-negative breast cancer (TNBC) treated by neoadjuvant chemotherapy and anti-EGFR antibodies (NAT), we evaluated tumor genomic, transcriptomic, and immune features, using MSK-IMPACT assay, gene arrays, Nanostring technology, and TIL assessment on H&E." (PMID 34535679, 2021).
triple-negative breast carcinoma (continued). "The recent development of dual-targeting antibodies against EGFR/PI3K/AKT and NOTCH signaling is encouraging, because this dual inhibitor decreased resistance and thus may gain clinical efficacy in triple-negative breast cancer." (PMID 32055024, 2020). "In vitro analysis indicated that it killed triple-negative breast carcinoma cell lines with EGFR overexpression but not lines that only expressed wildtype EGFR at normal levels." (PMID 32957689, 2020). "Berberine could downregulate IL-8 expression through inhibition of the EGFR/MEK/ERK pathway to suppress cell invasiveness and growth in triple-negative breast cancer cells." (PMID 32328135, 2020). "The human epidermal growth factor receptor (HER) family, notably EGFR, is overexpressed in most triple-negative breast cancer (TNBC) cases and provides cancer cells with compensatory signals that greatly contribute to the survival and development of resistance in response to therapy." (PMID 32414394, 2020). "Additionally, Annexin A2 interacts with Gal-3 at membrane lattices, which is important for EGFR/MAPK signaling in the survival, growth and progression of triple-negative breast cancer." (PMID 32268913, 2020). "The utility of this antibody was examined by constructing an immunotoxin and testing its activity against triple-negative breast cancer with EGFR amplification/overexpression but no expression of EGFRvIII." (PMID 32957689, 2020). "Similarly, triple-negative breast cancers with MT4-MMP, EGFR and RB-positive are sensitive to Erlotinib in combination with Palbociclib in PDX model." (PMID 31358010, 2019). "Epidermal growth factor receptor (EGFR) is over-expressed in about 50% of Triple negative breast cancers (TNBCs), but EGFR inhibitors have not been effective in treating TNBC patients." (PMID 28531218, 2017). "The combination of EGCG with cetuximab (antibody against EGFR) has recently been shown to exert strong anti-tumor activity against triple negative breast cancer orthoxenograft, without signs of toxicity." (PMID 27941682, 2016). "The proportion of CD44-positive [76.9 % (p < 0.05)] and EGFR-positive [67.2 % (p = 0.108)] cases in the triple-negative breast cancer (TNBC) group was higher than that of the non-TNBC group." (PMID 25429827, 2015). "Nevertheless, the clinical results in triple-negative breast cancer combined with the now significant body of preclinical data regarding the role of EGFR in IBC strongly suggest EGFR targeting should not be abandoned for IBC based on studies in non-IBC." (PMID 25887413, 2015). "A similar effect of perhexiline on decreasing HER3 expression was detected in triple-negative breast cancer MDA-MB-468 cells that express EGFR and HER3, but not HER2." (PMID 25849870, 2015). "While these results are far from encouraging, experimental data indicate that time-staggered EGFR inhibition, as opposed to simultaneous co-administration, can dramatically sensitize a subset of triple-negative breast cancer cells to genotoxic drugs." (PMID 26036637, 2015). "Nevertheless, its inhibitory effect on EGFR did not deliver clinical benefits for triple-negative breast cancer (TNBC) patients even EGFR overexpression was frequently found in this disease." (PMID 26513016, 2015). "Interestingly, two triple negative breast cancer lines, MDAMB468 and BT20, which are reported to have amplified EGFR also showed a synergistic interaction." (PMID 26095475, 2015). "In an earlier study of triple-negative breast cancer, patients with EGFR-positive had a less favorable prognosis and a poorer response to neoadjuvant chemotherapy than patients with EGFR-negative tumors." (PMID 25216514, 2014). "This hypothesis was tested by treating triple-negative breast cancer cell lines with these characteristics with inhibitors of PI3K and AKT and an antibody against EGFR and HER3." (PMID 23441137, 2013).
triple-negative breast carcinoma (continued). "Anti-epidermal growth factor receptor (EGFR) therapy has been tried in triple negative breast cancer (TNBC) patients without evaluation of molecular and clinical predictors in several randomized clinical studies." (PMID 24205362, 2013). "It is established that treatment with Herceptin leads to selective overexpression and activation of epidermal growth factor receptor (EGFR) and Src which further contributes to oncogenesis in Herceptin resistant and triple negative breast cancer (TNBC) patients." (PMID 22957061, 2012). "The tyrosine kinase receptor, epidermal growth factor receptor (EGFR), is a molecule overexpressed in triple-negative breast cancer (TNBC); that is, estrogen receptor-negative, progesterone receptor-negative, and HER2-negative." (PMID 22788954, 2012). "Triple-negative breast cancer (TNBC) is a subtype of invasive breast cancer characterized by negative expression of hormonal and HER2 receptors, and this subtype generally overexpresses EGFR." (PMID 21966417, 2011). "Although we have established that YB-1 and EGFR are frequently expressed in triple-negative breast cancers, it is not clear why this occurs." (PMID 17875215, 2007). "Therefore, the dual targeting of EGFR and HER-2 may be beneficial for EGFR over-expressing triple-negative breast cancer, for which CUDC-1010 would be an appealing HDACi candidate." (PMID 39598379, 2024). "Among them, EGFR is overexpressed in more than 50% of triple-negative breast cancer (TNBC), which is characterized by lack of estrogen receptor, progesterone receptor, and HER2 expression, associated with poor clinical outcome and has limited treatment approaches." (PMID 37095176, 2023). "EGFR (Epidermal growth factor receptor) overexpression has been detected in almost 1/3 of patients with highly aggressive inflammatory breast cancer (IBC) and in more than half of patients with triple-negative breast cancer (TNBC), which indicates a poor prognosis." (PMID 36983412, 2023). "Furthermore, integrin α5β1 binding to the secreted protein Tubulointerstitial nephritis antigen-like 1 (Tinagl1), which also involves αvβ1 and epidermal growth factor receptor (EGFR), results in suppressing triple-negative breast cancer progression and metastasis." (PMID 37681100, 2023). "However, molecular mechanisms of nuclear EGFR in triple-negative breast cancer (TNBC) have not been fully elucidated." (PMID 35013116, 2022). "In ERα-positive and triple-negative breast cancer (TNBC) cells (MDA-MB-231), BPA activates signal transduction pathways [i.e., extracellular signal-regulated kinase 1/2 (ERK1/2)] involved in proliferation via G-protein coupled estrogen receptor (GPER) and epidermal growth factor receptor (EGFR)." (PMID 33330580, 2020). "Indeed, high EGFR gene expression is not prognostic for poor survival in basal-like, triple-negative breast cancers according to the survival analysis tool used in this study (Kaplan-Meier Plotter)." (PMID 31139569, 2019). "EGFR expression is common in heterogeneous triple negative breast cancer (a cancer characterized by the lack of estrogen and progesterone hormone receptors and the HER2 receptor), and expression is associated with aggressive disease progression and poor survival rates." (PMID 29464085, 2018). "Moreover, the addition of EGFR inhibitor cetuximab to carboplatin did not improve outcomes in a randomized phase II trial in triple negative breast cancer (TNBC) patients." (PMID 26036637, 2015). "Combined inhibition of PI4KIIα and EGFR was more effective in inhibiting cell viability compared to single application of either method in the three cell lines as indicated, in particular in NSCLC A549 cells and the triple-negative breast cancer cell line MDA-MB231 cells." (PMID 24801752, 2014).